EGFR (epidermal growth factor receptor)
Diseases named in the same sentence as EGFR in open-access papers (continued):
Sharing a sentence is not in itself a finding about the gene and the disease.
lung adenocarcinoma (continued). "Lung adenocarcinomas with EGFR mutations exhibit reduced tertiary lymphoid structure (TLS) formation compared to those without EGFR mutations." (PMID 40723259, 2025). "EGFR mutations are generally associated with a subset of lung adenocarcinomas, particularly in East Asian populations, non-smokers, and females, while such mutations are not typically observed in primary pancreatic malignancies." (PMID 40656425, 2025). "EGFR-mutant lung adenocarcinoma was regarded as a cancer type with “immune-cold” and “immunosuppressive” properties; this is important to consider in the pursuit to unveil insights into tumor immune microenvironment in EGFR-mutant lung adenocarcinoma." (PMID 40723259, 2025). "Epicatechin and scopoletin induce apoptosis in leukemia (Jurkat, WEHI-3b) and lung adenocarcinoma (A549) through caspase-3/8 activation, G0/G1 arrest, and downregulation of tumor proliferation genes (EGFR, MDM2, RAF1, mTOR), while enhancing immune responses and reducing COX-2 expression." (PMID 41346617, 2025). "This case of advanced lung adenocarcinoma patient was transformed to SCLC resistant to one generation EGFR TKIs treatment, and the front-line treatment after transformation was a regimen of anlotinib in combination with EP, which resulted in the patient achieving a long PFS." (PMID 39995840, 2025). "In the current study, we employed multiplex fluorescent IHC staining to identify the tertiary lymphoid structures (TLSs) in early-stage EGFR-mutant lung adenocarcinoma patients, despite this cancer type being previously characterized as “immune-cold” and “immunosuppressive”." (PMID 40723259, 2025). "All patients harboring Y772_A775dup and G778_P780dup were diagnosed with lung adenocarcinoma and were predominantly females, nonsmokers, or light smokers, similar to patients with lung adenocarcinoma with EGFR mutations." (PMID 41154672, 2025). "In addition in murine xenograft model of human lung adenocarcinoma the Authors confirmed that Ad-mediated EGFR oncogene-specific Cas9 expression can disrupt the EGFR mutant allele in H1975 cells with high accuracy in vivo." (PMID 40428391, 2025). "The discovery of activating epidermal growth factor receptor (EGFR) mutations, which respond to EGFR tyrosine kinase inhibitors (TKIs), was initially made in Asian women and non-smokers with lung adenocarcinoma." (PMID 39926430, 2025). "For example, in a cohort of patients with EGFR‐mutant lung adenocarcinoma, high PD‐L1 expression was associated with early resistance to first‐generation EGFR‐TKIs and shorter survival, regardless of ethnicity." (PMID 41308037, 2025). "In EGFR-driven lung adenocarcinomas, AMs support tumor growth by providing nutrients." (PMID 40777028, 2025). "Metabolic shift toward OXPHOS are considered a distinctive metabolic trait of drug resistance in cancer, while targeting OXPHOS abates resistance to 5-fluorouracil in colon cancer, docetaxel in prostate cancer, MAPK inhibitor in melanoma, and EGFR-TKI in EGFR-driven lung adenocarcinoma." (PMID 40612109, 2025). "We also analyzed the relationship between RacGAP1 expression and common lung adenocarcinoma driver gene state (mutated and non-mutated), in particular EGFR, ALK and K-RAS, finding no obvious and significant difference." (PMID 40497948, 2025). "A 48-year-old non-smoker male was diagnosed with lung adenocarcinoma with EGFR L858R mutation with diffuse bone metastases." (PMID 40104434, 2025). "We also ascertained that neither the PD-L1 tumor proportion score (TPS) nor the EGFR mutation subtype correlated with the expression of TLSs in early-stage EGFR-mutant lung adenocarcinoma patients." (PMID 40723259, 2025). "The treatment plan for coexistent TB and EGFR-mutated lung adenocarcinoma is not clear, considering the drug interactions between rifampicin and targeted therapies." (PMID 41141063, 2025).
lung adenocarcinoma (continued). "While EGFR mutations are rarely observed in primary pancreatic adenocarcinomas, they are well-established oncogenic drivers in lung adenocarcinomas, particularly in Asian populations and non-smokers." (PMID 40656425, 2025). "Notably, EGFR and KRAS mutations, which are common in lung adenocarcinoma, activate key signaling cascades such as MAPK/ERK and PI3K/AKT, which in turn modulate the expression of several oncogenic lncRNAs." (PMID 40650307, 2025). "This approach has shown potential in lung adenocarcinoma treatments with EGFR-targeting TKIs, such as osimertinib, where data from clinical trials (e.g., NEJ002-NCT00322452 and FLAURA-NCT02296125) has been used to align model predictions with actual patient outcomes." (PMID 39790707, 2025). "A recent investigation found that macrophage infiltration differed between EGFR-mutant and WT lung adenocarcinoma, and some specific macrophage populations might regulate the response to ICI." (PMID 41162774, 2025). "Lung adenocarcinoma, for instance, could be further classified based on driving mutations in KRAS and/or EGFR genes." (PMID 41269529, 2025). "In addition, PM2.5 exposure increases IL-1β release from macrophages, encouraging a progenitor-like state in EGFR-mutant alveolar type II cells, which are precursors to lung adenocarcinoma." (PMID 39578555, 2025). "They formulated that carrying EGFR mutations was obviously associated with the absence of ILD in patients with lung adenocarcinoma (OR: 17.41, 95% CI: 3.54–315.34, p < 0.001), independent of gender and smoking status." (PMID 40507634, 2025). "TTF-1, CK7, and Napsin A positivity on IHC confirmed lung adenocarcinoma, a disease increasingly seen in non-smokers due to factors such as genetic mutations (e.g., EGFR, ALK) and environmental exposures." (PMID 40821205, 2025). "The PIONEER study also demonstrated a high EGFR mutation rate (51.4%) in Asian women and non-smokers with lung adenocarcinoma." (PMID 41378298, 2025). "Additionally, we examined the clinical association between the programmed death-ligand 1 (PD-L1) tumor proportion score (TPS) and TLSs in early-stage EGFR-mutant lung adenocarcinoma patients." (PMID 40723259, 2025). "For example, in EGFR-mutant lung adenocarcinoma cells, metformin inhibits mitochondrial electron transport complex 1 to induce AMPK activation, leading to the inhibition of the mTOR pathway, which causes G0/G1 cell cycle arrest, mitochondrial apoptosis, and reduction of tumor growth." (PMID 40983975, 2025). "Further analysis of the qualitative and quantitative parameters of three-dimensional CT in patients with different EGFR and ALK gene rearrangements revealed that the BS, PIS, VBS, MND, NV, ACTV, and SCP were correlated with EGFR mutation in GGO-associated lung adenocarcinoma." (PMID 41020204, 2025). "Despite advances in EGFR-TKIs for lung adenocarcinoma (LUAD), resistance remains a major hurdle." (PMID 41358202, 2025). "Similarly, in epidermal growth factor receptor (EGFR) mutant lung adenocarcinoma, a TKI, osimertinib, demonstrated remarkable efficacy in patients with LMD, achieving a durable clinical response up to one year in the BLOOM study." (PMID 40710887, 2025). "Moreover, HGF was found to activate the PI3K/Akt signaling pathway in EGFR-mutant lung adenocarcinoma, facilitating tumor cell proliferation." (PMID 40003951, 2025). "In conclusion, we report a refractory lung adenocarcinoma patient with extensive leptomeningeal metastases, harboring EGFR and somatic BRCA2 co-mutations, who exhibited a lasting response to Olaparib despite resistance to third-generation EGFR-TKIs." (PMID 40182045, 2025).
lung adenocarcinoma (continued). "Molecular profiling, particularly identifying the EGFR exon 21 L858R mutation, reinforced the suspicion of lung adenocarcinoma as the primary source despite the absence of detectable primary lung lesions on imaging." (PMID 40740944, 2025). "Therefore, it is important to find the therapeutic biomarker for preventing recurrence and prolonging survival in early-stage EGFR-mutant lung adenocarcinoma patients." (PMID 40723259, 2025). "Background/Objectives: The role of tertiary lymphoid structures (TLSs) in cancer prognosis is well established, yet their significance in early-stage EGFR-mutant lung adenocarcinoma remains unclear." (PMID 40723259, 2025). "The study concluded that specific radiological and pathological characteristics, along with EGFR and ALK mutation statuses, could be used to guide the treatment and diagnosis of lung adenocarcinoma." (PMID 41378298, 2025). "IMA has a higher rate of ALK rearrangement mutations (2.2%) and a lower rate of EGFR mutations (0–5%) than nonmucinous adenocarcinoma of the lung." (PMID 38303008, 2024). "In this study, we selected a panel of lung adenocarcinoma cell lines harboring major mutations commonly found in LUAD tumors, more specifically mutations of EGFR (H1975), KRAS (PF139) and BRAF (PF901) oncoproteins, furthermore, we also included one cell line with no known driver mutations (H838)." (PMID 39227650, 2024). "Therefore, the present study aimed to investigate the mechanism of PD-L1 in primary resistance to EGFR–TKIs in EGFR-mutant lung adenocarcinoma (LUAD) cells." (PMID 39090096, 2024). "Combining epidermal growth factor receptor (EGFR) tyrosine kinase inhibitor (TKI) with an anti‐ vascular endothelial growth factor (VEGF) agent, bevacizumab or ramucirumab, is indicated for advanced lung adenocarcinoma harboring EGFR mutation." (PMID 38523603, 2024). "Small-cell lung cancer (SCLC) transformation accounts for 3-14% of resistance in EGFR-TKI relapsed lung adenocarcinomas (LUADs), with unknown molecular mechanisms and optimal treatment strategies." (PMID 39353908, 2024). "Therefore, PET/CT and EGFR gene testing are necessary in the predictive analysis of brain metastasis of lung adenocarcinoma." (PMID 38605303, 2024). "Previous study suggested that females and never smokers with lung adenocarcinoma are more likely to harbor EGFR/ALK/ROS1 mutation." (PMID 39000058, 2024). "Additionally, we included patients from The Cancer Genome Atlas lung adenocarcinoma dataset with both CT images and RNA sequencing data to explore the biological associations between EME score and EGFR-related biological processes." (PMID 38361006, 2024). "Using single-cell RNA-sequencing (RNA-seq) datasets from lung adenocarcinoma (LUAD), this study constructed an R-loop scoring model to characterize the R-loop state based on the identified R-loop regulators related to EGFR mutations, tissue origins, and TNM stage." (PMID 38200551, 2024). "TR64 (stage IIIA, adenocarcinoma, 71-year-old male, non-smoker) has an EGFR missense mutation c.2573T>G characterized as pathogenic with moderate impact on protein function and reported in lung adenocarcinoma." (PMID 38893104, 2024). "Indeed, YY1 gene expression was unrelated to EGFR status in lung adenocarcinoma from the Cancer Genome Atlas." (PMID 39604408, 2024). "Along with the high frequency of epidermal growth factor receptor (EGFR) activating mutations, the early onset of lung adenocarcinoma (LUAD) among never-smokers in this region is suggestive of a genetic contribution towards disease presentation." (PMID 38539567, 2024). "ALK rearrangements are found in a similar population to EGFR mutations, namely among patients with lung adenocarcinoma, light or never-smokers, and a younger age at diagnosis." (PMID 38347643, 2024).
lung adenocarcinoma (continued). "At this concept, a study evaluated KRAS mutations in minor clones in patients with lung adenocarcinoma treated with EGFR-TKI, concluding that KRAS mutations might hinder the effectiveness of anti-EGFR therapy." (PMID 38793038, 2024). "All patients were Japanese with lung adenocarcinomas and received EGFR monotherapy." (PMID 39156250, 2024). "In a mouse model of EGFR-mutated lung adenocarcinoma, which has a non-inflammatory immunosuppressive tumor microenvironment, EGFR signaling recruits CD4+ regulatory T cells and CD8+ T cell infiltration by activating JNK/cJun and inhibiting IRF1." (PMID 38762484, 2024). "The scarcity of proteogenomic research on lung adenocarcinoma in never smokers without EGFR or ALK mutations has resulted in an oversimplified view of these diseases, treating them collectively as a single, homogeneous, yet undefined entity." (PMID 39300154, 2024). "Gene mutations observed differ between lung adenocarcinoma and lung squamous cell carcinoma, with KRAS, EGFR, LPHN3, KEAP1, and TLR4 being relatively common in lung adenocarcinoma, whereas BAI3, FBXW7, GRM8, ERBB4, MUC16, and RUNX1T1 are common in lung squamous cell carcinoma." (PMID 39594843, 2024). "Targeting the PDPN/MET signaling axis may be a potential therapeutic strategy to overcome resistance to EGFR-TKIs in lung adenocarcinoma patients." (PMID 39403603, 2024). "The patient was diagnosed with stage IV lung adenocarcinoma with EGFR 19del." (PMID 39234244, 2024). "For example, the inhibition of mutant-EGFR in lung adenocarcinoma cells or mutant-BRAF in thyroid cancer cells was shown to induce the secretion of IL6 and the subsequent activation of STAT3, and in both cases, blocking the STAT3 function largely prevented the emergence of drug-tolerant cells." (PMID 38473364, 2024). "Previous research has shown that EGFR mutations and KRAS mutations rarely occur together, and the use of EGFR-targeted drugs alone to treat KRAS-mutant lung adenocarcinoma has not shown significant clinical benefits." (PMID 38734764, 2024). "In this study, using single-cell RNA-sequencing datasets from lung adenocarcinoma (LUAD), we constructed an R-loop scoring model to characterize the R-loop state according to the identified R-loop regulators related to EGFR mutations, tissue origins, and TNM stage." (PMID 38200551, 2024). "PPARγ agonist efatutazone could induce the cell cycle arrest and apoptosis of EGFR-TKI-resistant lung adenocarcinoma cells via PPARγ/phosphatase and tensin homolog (PTEN)/Akt pathway." (PMID 38397426, 2024). "Ten pairs of EGFR wild lung adenocarcinoma cancer tissue and paracancerous tissue samples, as well as nine pairs of EGFR mutant lung adenocarcinoma cancer tissue and paracancerous tissue samples were obtained from the First Affiliated Hospital of Zhengzhou University." (PMID 39343971, 2024). "EGFR mutations are commonly detected in most Asian lung adenocarcinoma non-smokers and are closely associated with dramatically response to the EGFR-TKIs." (PMID 37436674, 2024). "In lung adenocarcinoma, PTK7 was found to be overexpressed in cancer tissues compared to normal lung tissues, and the positivity of PTK7 expression was higher in cases with ALK mutations and lower in cases with EGFR mutations." (PMID 39474113, 2024). "Additionally, in lung adenocarcinoma, F2R has been identified as a promoter of tumor angiogenesis via the EGFR pathway." (PMID 39655193, 2024). "Similarly, the previous study demonstrated that high E-cadherin expression in the lung tumor was associated with worse overall survival in patients with stage IV EGFR-mutant lung adenocarcinoma." (PMID 38720340, 2024).
lung adenocarcinoma (continued). "We first utilized TCGA never-smoker lung adenocarcinomas without EGFR or ALK driver mutations (n = 46)." (PMID 39300154, 2024). "In EGFR-driven lung adenocarcinoma (LUAD), tumor-associated alveolar macrophages (TA-AMs) can reduce EGFR phosphorylation and inhibit LUAD progression by enhancing GM-CSF-PPARγ signaling and suppressing PPARγ-driven signaling to inhibit cholesterol flux toward tumor cells." (PMID 38954021, 2024). "Another controversial finding was in the field of lung adenocarcinoma, where it was found that PTK7 expression correlates with lymph node metastasis, and that high PTK7 expression implies a higher rate of ALK mutation and a lower rate of EGFR mutation." (PMID 39474113, 2024). "Furthermore, the MHC class I genes have been reported to be silenced in EGFR-mutant lung adenocarcinoma upon lineage transformation to small cell lung cancer." (PMID 38405800, 2024). "This was also fully demonstrated in a retrospective study of nearly 500 patients with lung adenocarcinoma, with a higher frequency of EGFR mutations in the TB group than in the non-TB group (56% vs 34%, p=0.038)." (PMID 38298194, 2024). "According to the literature the EGFR mutation-specific antibodies have a fair sensitivity and high specificity in identifying lung adenocarcinomas with classic EGFR mutations, while they do not recognise uncommon EGFR mutations." (PMID 38953007, 2024). "In conclusion, in pathologic stage I (> 2 cm) lung adenocarcinomas with EGFR mutation, no survival benefit of adjuvant chemotherapy with UFT was observed." (PMID 39255996, 2024). "Our initial analysis specifically focused on 69 lung adenocarcinoma (LUAD) cell lines without oncogenic EGFR/ALK mutations." (PMID 39300154, 2024). "However, our study preliminarily demonstrates the feasibility of machine learning-based PET/CT radiomics combined with EGFR analysis in predicting brain metastasis of lung adenocarcinoma." (PMID 38605303, 2024). "This case report examines the effectiveness of osimertinib in a 64-year-old non-smoking female diagnosed with stage IV lung adenocarcinoma and an epidermal growth factor receptor (EGFR) exon 19 mutation, focusing on the treatment’s impact on bone metastasis." (PMID 39108772, 2024). "The clinical value and impact in patients with EGFR mutation on survival outcomes is further needed to be elucidated to decide whether the application of EGFR-TKIs was appropriate in early lung adenocarcinoma (LUAD) stage appearing as subsolid nodules." (PMID 38528507, 2024). "Additionally, in the treatment of a lung adenocarcinoma in our center, we also established the feasibility of such combination therapy after EGFR TKI resistance." (PMID 39354638, 2024). "An investigation reported that EGFR-mutated lung adenocarcinomas typically have a non-inflamed TME yet exhibit significant infiltration of CD4+ effector Tregs, which are more common in inflamed TMEs." (PMID 39015563, 2024). "EGFR and ALK mutation can be seen between 12–17 and 5–7% of the lung adenocarcinoma, respectively." (PMID 38668879, 2024). "In the NSCLC population with EGFR ex20ins mutations, Asian women younger than 60 years without a smoking history had a higher incidence of lung adenocarcinoma." (PMID 38774882, 2024). "Some studies have suggested that lung adenocarcinoma, women, and non-smokers were positively associated with EGFR mutations." (PMID 39364008, 2024). "Genetic mutations are found in 90% of nonsmoking female lung adenocarcinoma patients, with EGFR mutations being the most common." (PMID 39315583, 2024). "Patients with uncommon EGFR-mutated lung adenocarcinoma for whom treatment guidelines in 2019 and 2020 were lacking and who were treated with on-label targeted therapy demonstrated relatively high response rates and long PFS." (PMID 39500140, 2024). "In the present study, we found that five FDG PET texture indices, but not SUVmax, were related with the EGFR mutation status in patients with newly diagnosed lung adenocarcinoma." (PMID 37185611, 2023).